KCNA5 (potassium voltage-gated channel subfamily A member 5)
Description:
Voltage-gated potassium channel that mediates transmembrane potassium transport in excitable membranes. Forms tetrameric potassium-selective channels through which potassium ions pass in accordance with their electrochemical gradient. The channel alternates between opened and closed conformations in response to the voltage difference across the membrane. Can form functional homotetrameric channels and heterotetrameric channels that contain variable proportions of KCNA1, KCNA2, KCNA4, KCNA5, and possibly other family members as well; channel properties depend on the type of alpha subunits that are part of the channel. Channel properties are modulated by cytoplasmic beta subunits that regulate the subcellular location of the alpha subunits and promote rapid inactivation. Homotetrameric channels display rapid activation and slow inactivation. Required for normal electrical conduction including formation of the infranodal ventricular conduction system and normal action potential configuration, as a result of its interaction with XIRP2 (By similarity). May play a role in regulating the secretion of insulin in normal pancreatic islets. [Isoform 2]: Exhibits a faster depolarization rate, reduced voltage-dependent recovery from inactivation and an excessive cumulative inactivation.
Synonyms: Kv1.5; HK2; HPCN1; ATFB7; HCK1; PCN1
Tractability: Small molecule: an approved drug acts on it; a high-quality ligand is known; it belongs to a druggable protein family. Antibody: UniProt places it where antibodies can reach, with high confidence; its Gene Ontology location is reachable by antibodies, with high confidence; UniProt predicts a signal peptide or a membrane-spanning region. PROTAC: UniProt records ubiquitination sites on it; a small molecule that binds it is known.
Target class: Potassium channels; Ion channel; Voltage-gated ion channel; Voltage-gated potassium channel
Gene: Protein-coding gene on chromosome 12 (5,043,879 to 5,046,788, forward strand). Ensembl gene ENSG00000130037.
Subcellular location: Cell membrane
Pathways (Reactome):
Muscle contraction: Phase 3 - rapid repolarisation
Neuronal System: Voltage gated Potassium channels
Gene Ontology:
Molecular function: alpha-actinin binding; delayed rectifier potassium channel activity; outward rectifier potassium channel activity; protein binding; protein kinase binding; scaffold protein binding; voltage-gated potassium channel activity; voltage-gated potassium channel activity involved in atrial cardiac muscle cell action potential repolarization; voltage-gated potassium channel activity involved in bundle of His cell action potential repolarization; voltage-gated potassium channel activity involved in SA node cell action potential repolarization; monoatomic ion channel activity; signaling receptor binding
Biological process: atrial cardiac muscle cell action potential; membrane hyperpolarization; membrane repolarization during atrial cardiac muscle cell action potential; membrane repolarization during bundle of His cell action potential; membrane repolarization during SA node cell action potential; potassium ion export across plasma membrane; potassium ion transmembrane transport; potassium ion transport; regulation of atrial cardiac muscle cell membrane repolarization; regulation of heart rate by cardiac conduction; regulation of membrane potential; action potential; regulation of insulin secretion; monoatomic ion transport; negative regulation of cytosolic calcium ion concentration; positive regulation of G1/S transition of mitotic cell cycle; positive regulation of myoblast proliferation; potassium ion homeostasis; protein complex oligomerization; protein homooligomerization; response to hydrogen peroxide; response to hyperoxia; response to hypoxia; response to mechanical stimulus; transmembrane transport
Cellular component: cell surface; Golgi apparatus; intercalated disc; membrane raft; plasma membrane; potassium channel complex; voltage-gated potassium channel complex; caveola; membrane; intracellular canaliculus; perinuclear region of cytoplasm; Z disc
Genetic constraint (gnomAD): Loss-of-function variants: 23 observed, 27.56 expected, observed/expected ratio (o/e) 0.83, 90% interval 0.6 to 1.18. The synonymous counts are far from expectation, so gnomAD's model fits this gene poorly and the ratio says little. Missense variants: 916 observed, 856.95 expected, observed/expected ratio (o/e) 1.07, 90% interval 1.01 to 1.13. Synonymous variants: 465 observed, 380.49 expected, observed/expected ratio (o/e) 1.22, 90% interval 1.13 to 1.32.
Homologues: Orthologues: chimpanzee KCNA5 (98% identical), macaque KCNA5 (97% identical), dog KCNA5 (88% identical), pig KCNA5 (87% identical), rabbit KCNA5 (87% identical), mouse Kcna5 (86% identical), rat Kcna5 (86% identical), guinea pig KCNA5 (84% identical), tropical clawed frog kcna5 (66% identical). Paralogues in human: KCNA3 (55% identical), KCNA2 (55% identical), KCNA1 (54% identical), KCNA4 (54% identical), KCNA6 (53% identical), KCNA10 (50% identical), KCNA7 (46% identical), KCNC4 (30% identical), KCNC3 (30% identical), KCNC2 (29% identical), KCND1 (28% identical), and 19 more.